MIR3677HG (MIR3677 and MIR940 host gene)
Gene: Long non-coding RNA gene on chromosome 16 (2,267,881 to 2,273,428, forward strand). Ensembl gene ENSG00000260778.
Gene Ontology:
Biological process: miRNA-mediated post-transcriptional gene silencing
Cellular component: RISC complex